CXCR1 (C-X-C motif chemokine receptor 1)
Diseases named in the same sentence as CXCR1 in open-access papers (continued):
Sharing a sentence is not in itself a finding about the gene and the disease.
cancer (continued). "The IL-8/CXCR1 signaling axis, in particular, has garnered attention for its role in enhancing the malignant phenotype of cancer cells." (PMID 38891100, 2024). "The role of CXCR1/2 signaling in cancer has been primarily investigated in preclinical models regarding its ability to promote the migration of myeloid cells." (PMID 39639338, 2024). "Recent studies have demonstrated that CARs modified with CXCR1/2 significantly enhance the migration and persistence of T cells in various cancers, including glioblastoma, ovarian cancer, pancreatic cancer, and hepatocellular carcinoma." (PMID 38516299, 2023). "Prior research has shown that the up-regulated expression of CXCR1 or CXCR2 ligands, specifically CXCL1, CXCL2, and CXCL8, is linked to chemoresistance and suspected to hamper the anti-cancer immune response." (PMID 37509721, 2023). "AGE-RAGE driven surge in pro-inflammatory cytokine IL-8 in CAFs, activating CXCR1/2 receptors, incite deregulated inflammatory micro-milieu leading to cancer progression." (PMID 37970208, 2023). "CXCR1 is physiologically found on granulocytes, monocytes, mast cells and natural killer cells, but also on cancer cells and the TME, where the signaling mediates immunosuppressive responses." (PMID 37507547, 2023). "CXCR1 and CXCR2 are receptors for interleukin-8 (IL-8), a chemokine primarily produced by cancer cells that is known for its function in attracting polymorphonuclear inflammatory leukocyte infiltrates acting on CXCR1/2." (PMID 38516299, 2023). "In this study, we found that CXCR1 showed decreased expression in cancer samples, indicating that P and S have similar functions on CXCR1." (PMID 36647133, 2023). "Activation of CXCR1/2 by CXCL genes is a key factor regulating the recruitment of neutrophils into the cancer site." (PMID 37540227, 2023). "Many cancer cells exhibit induction or increased expression of multiple ligands for both CXCR1 (CXCL1-3, 5–8) and CXCR2 (CXCL1-3, 5 and 7)." (PMID 37270599, 2023). "CXCR1 is becoming more well known for its role as a cancer stem cell identifier and therapeutic target." (PMID 36831112, 2023). "This IL-8 from CAFs via paracrine signals prompt CXCR1/2, in turn resulting in the derivation of migratory and invasive characteristics in cancer cells." (PMID 37970208, 2023). "Endogenous CXCR1 can not only directly interfere with the resistance of cancer cells to chemotherapeutic drugs, but also be an active regulator of cancer cell metastasis." (PMID 36325326, 2022). "Chemokines CXCL1, 2, 5, 6, 8 and their receptors CXCR1/2 are co-opted by multiple cancers to facilitate the recruitment of neutrophils." (PMID 35585567, 2022). "Another CXCR1/2 inhibitor, SX-682, an orally available small molecule, blocks the entry of MDSCs into cancer and can promote an immune response to cancer." (PMID 35269786, 2022). "The chemokine ligands for CXCR1/2 are expressed and secreted by different cancer cell types, and these ligands stimulate proliferation and migration by acting in an autocrine fashion." (PMID 36118530, 2022). "Recent research advances have shown that CXCR1 is not only a key therapeutic target in many cancers, but also plays an important role in other diseases." (PMID 36325326, 2022). "In recent years, a variety of biological functions of CXCR1 in vivo have been discovered, and it is most reported in cancer." (PMID 36325326, 2022). "Hypoxia and hypoxia-activated signaling pathways are effective targets in cancer therapy, where the former can cause alterations in the expression of CXCL7 and its receptor CXCR1/2 in tumors." (PMID 35837284, 2022). "The interaction between IL-8 from adipocytes and C-X-C chemokine receptor type-1 (CXCR1) on cancer cells activates the p38MAPK/STAT3 phosphorylation pathway initiating metastasis." (PMID 35269636, 2022). "Among these, inflammatory cytokine CXCL8 and its receptor CXCR1/2 axis have a confirmed regulatory role in pro-inflammation, cancer cell multiplication, invasion and metastasis." (PMID 35922850, 2022).
cancer (continued). "With the deepening of research, CXCR1 is regarded as a novel therapeutic target in various cancer treatments." (PMID 36325326, 2022). "There are several cancer-related processes in which these genes are involved, and some of them (e.g., CXCR1) have multiple functions." (PMID 35875133, 2022). "The interaction between CXCL8 and CXCR1/2 regulates the trafficking of cells for cancer progression in the TME." (PMID 34025668, 2021). "Taken together, our data demonstrate that PERK-C/EBPδ-dependent factors secreted from cancer cells after exposure to thapsigargin modulate myeloid cell gene expression through activation of CXCR1/2 receptors." (PMID 34725321, 2021). "This approach targeted in particular a metastatic subpopulation of cancer cells responsive to IL-8 stimulation via CXCR1." (PMID 35011682, 2021). "In particular, CXCL8 is increased in inflammation, while CRC is increased through CXCR1 and is involved in cells transition from normal to carcinoma." (PMID 34944856, 2021). "In zebrafish, cancer cells recruit neutrophils through chemokine receptors Cxcr1 and 2 and their Cxcl8 ligands." (PMID 32161595, 2020). "IL-8 is released by cancer cells and binds to G protein-coupled receptors C-X-C motif chemokine receptor 1 and 2 (CXCR1 and CXCR2) on MDSCs." (PMID 33384962, 2020). "We report herein the identification and biological characterization of a new series of CXCR1/2 inhibitors with significant anti-cancer effects." (PMID 31410218, 2019). "IL-8 has been reported to induce cancer cell invasion by interacting with its receptors, CXCR1 and CXCR2, on the surface of cancer cells." (PMID 31684995, 2019). "Here, we described the relevance of targeting the ELR+CXCL cytokines receptors, CXCR1/2, for the treatment of these two cancer types." (PMID 31410218, 2019). "Previous studies have demonstrated that CXCL8 and CXCL7 regulated the progression of various cancers via binding to CXCR1 and CXCR2." (PMID 30984000, 2019). "Recently, the role of CXCR1/2 signaling in cancer and inflammatory diseases has been extensively reviewed." (PMID 31390756, 2019). "Interleukine-8 (IL-8) is associated with cell proliferation, migration, and invasion in cancer by activating C-X-C motif chemokine receptor 1 (CXCR1) and CXCR2, two cell surface G-protein coupled receptors." (PMID 30154469, 2018). "Neutrophils from healthy donors and cancer patients had similar expression of the chemokine receptors CXCR1 and CXCR2." (PMID 30323345, 2018). "As all of our cases were characterized by early recurrence and metastasis due to vascular invasion and as all carcinomas express CXCR1, our observation is consistent with this." (PMID 29976164, 2018). "Three genes, CD40, OAS2, and CXCR1, were identified as potential biomarkers of normal tissue toxicity in cancer patients after radiotherapy." (PMID 28443095, 2017). "CXCR1, also known as interleukin-8 receptor A, has been demonstrated to play important role in the proliferation, invasion, angiogenesis and metastasis of cancer cells." (PMID 28927426, 2017). "The apparently divergent effect of reparixin combination on neural and cancer cells functionality is coherent with the specific pathways activated by CXCR1/2 receptors in the two different cellular contexts." (PMID 28423567, 2017). "CXCR1 has proved to be correlated with a number of cancers, including breast cancer, prostate cancer, colorectal cancer and lung cancer." (PMID 27780937, 2017). "The blocking of IL-8 by siRNA reduced CXCR1/2 expression in HNSCC cells, suggesting that the cancer progression of HNSCC cells that is induced by IL-8 depends on CXCR1/2." (PMID 27557518, 2016). "Experimental results reveal that IL-8 upregulates CXCR1 and CXCR2 expression, suggesting that the cancer progression of HNSCC cells that is induced by IL-8 depends on both CXCR1/2 receptors." (PMID 27557518, 2016).
cancer (continued). "In all three patients who progressed for whom tissue was available, strong CXCL1 expression in cancer cells was observed in all cases and infiltrating CXCR1-bright cells in two of three cases." (PMID 27241286, 2016). "In turn, blocking of IL-8 signaling by antibodies against IL-8 or its receptor CXCR1 reduced survival and cancer stemness significantly." (PMID 26840266, 2016). "In contrast, 88% of obese patients with low-grade cancer had a high presence of CXCR1-bright cells in the prostate stroma." (PMID 27241286, 2016). "Cytokine receptors CCR5 and CXCR1 were also identified as cancer essential proteins and this is confirmed by other studies." (PMID 26565620, 2015). "ELR-CXC chemokines stimulate a wide array of downstream signaling molecules through binding to CXCR1 and CXCR2, among which activation of MAPK and AKT is closely implicated in cancer development and progression." (PMID 26087179, 2015). "Despite this extensive pre-clinical literature, there has been limited exploitation of this knowledge in clinical trials aimed at evaluating anti-CXCL8 or CXCR1/2 inhibitors as anti-cancer therapeutics." (PMID 24276377, 2013). "The remainder of this review will focus on elucidating some of the principal strategies available for targeting CXCL8-CXCR1/2 signaling in cancer, both indirectly with the use of anti-inflammatories, and directly, using CXCL8- or CXCR1/2-targeted inhibitors." (PMID 24276377, 2013). "The abnormal expression of CXCR1/2 in various types of malignant tumors has been reported, but less is known with regard to gastric carcinoma." (PMID 23420470, 2013). "Table summarizing the best characterized CXCR1/2 small molecule antagonists available from a range of pharmaceutical companies, and the pre-clinical cancer studies and clinical trials in other inflammatory conditions in which they have be utilized." (PMID 24276377, 2013). "CXCL8 or CXCR1/2-promoted angiogenesis has also been observed in numerous other cancer types, including melanoma, pancreatic, colon, and non-small cell lung cancer." (PMID 24276377, 2013). "Increased AKT expression and activity by CXCR1/2 receptor/ligand signaling have been detected in multiple forms of cancer, which is consistent with poor tumor progression." (PMID 23420470, 2013). "There is an extensive body of evidence to support the use of a CXCR1/2-targeted therapy in the treatment of human cancers." (PMID 24276377, 2013). "Notably, IL-8 has been shown to exert stimulatory effects on cancer stem cells in breast, colon, and pancreatic cancers via its receptors CXCR1/2." (PMID 40683891, 2025). "Furthermore, polymorphisms in genes encoding members of both CXCL8:CXCR1/2 and the VEGF:VEGFR signaling axes are linked to morbidity and response to anti-VEGF therapy in angiogenic diseases, including AMD and cancers." (PMID 41176546, 2025). "In one of the most extensive review on the classification of M-MDSCs, CXCR1 and CD84 appeared as the two new phenotypic markers associated with their immunosuppressive activity that have been added for the classification of M-MDSCs in cancer." (PMID 37243699, 2023). "It is expected to indirectly reduce the probability of peritoneal metastasis by developing a series of drugs targeting CXCL8 or CXCR1/2, or by improving the treatment effect of intraperitoneal chemotherapy on patients, slowing the deterioration of cancer after peritoneal metastasis." (PMID 37377954, 2023). "US clinical trials using CXCR1 antagonists for cancer treatment." (PMID 37114134, 2023). "Previous studies showed that the IL-8/CXCR1 axis could increase properties of cancer stemness, indicating that the involvement of REEP6 in the drug resistance of TSCC might be associated with the IL-8/CXCR1 axis." (PMID 37238941, 2023). "There could be a difference in downstream effectors separating CXCR1 and CXCR2, which leads CXCR1 to be a rising cancer stem cell (CSC)-like marker in several solid tumors." (PMID 36831112, 2023).
cancer (continued). "CXCR2 expression was significantly associated with cancer nest MMP9 expression (p = 0.010) whereas CXCR1 was not (p = 0.591)." (PMID 37296952, 2023). "In addition to IL-8, other chemokine ligands for CXCR1/2 can regulate stemness, although this depends on the specific ligand and cancer type." (PMID 36118530, 2022). "Besides, the combination of CXCR1/2 inhibitors with chemotherapy, anti-angiogenesis drugs, and immunotherapy is also a prospective strategy in cancer therapy." (PMID 35585567, 2022). "A three dimensional model of endothelial cells and cancer stem like cells generated the conditional niche through elevated levels of the IL-8 and IL-8 homologous receptors CXCR1/2, which enhanced the migration, growth, and dryness characteristics of cancer stem-like cells." (PMID 35574466, 2022). "Most recently, a single-center analysis of multiple genes involved in tumor inflammation and angiogenesis revealed CXCR1 (interleukine-8-receptor alpha—IL-8RA) +860 C>G heterozygous polymorphism to be an independent prognostic factor for DFS, cancer-specific survival and OS in patients with pCCA." (PMID 35205774, 2022). "CXCR1 and its role in cancer is well documented in the literature." (PMID 35875133, 2022). "In addition, activation of the CXCL8 receptor CXCR1 during thapsigargin exposure supported subsequent sphere formation by cancer cells." (PMID 34725321, 2021). "•CXCR1/2 inhibitors represent a new class of anti-cancer drugs." (PMID 34430714, 2021). "Altogether this makes the CXCR1/2 -CXCL8 pathway a target for cancer therapy." (PMID 34944943, 2021). "Besides, E-cadherin is a cell adhesion molecule involved in cell-cell and cell-matrix interactions and EMT process of cancer cells, and it reduces the aggressiveness of cancer cells; reportedly, CXCR1 knockdown increases E-cadherin expression in GC cells." (PMID 34516330, 2021). "Consequently, activated FOXC1 transactivates CXC chemokine receptor 1 (CXCR1), a crucial promoter of cancer cell motility through activation of Rho-GTPases, that increases invasion and metastasis in HCC." (PMID 34540690, 2021). "CXCR1 mediates the progression of multiple cancers, including GC." (PMID 34516330, 2021). "Cancer stem cells were the target of reparixin activity, through inhibition of CXCR1." (PMID 34476645, 2021). "Given its key role in host defense, the most effective strategies to neutralize the pro-tumorigenic effects of endogenous G-CSF in the setting of adjunctive anti-cancer therapy are likely to involve pharmacologic targeting of the CXCR1 and CXCR2 chemokine receptors." (PMID 33233675, 2020). "Three CXCR1/2 antagonists, namely the small chemical entities, reparixin (formerly known as repertaxin), SX-682 and navarixin (MK-7123) have recently entered the clinical arena of adjunctive therapy of cancer." (PMID 32244751, 2020). "Parallel genome-scale loss of function screens in 216 cancer cell lines implicate that IL-8, CXCR1 or CXCR2 knockdown has a negative impact on cell survival and proliferation." (PMID 33277516, 2020). "Considering the pleiotropic effects of CXCL8 in cancer (e.g., angiogenesis), and the hypothesized mechanism of action of CXCR1 inhibition on CSC, a number of markers were investigated on core biopsy samples by IHC." (PMID 31924241, 2020). "The IL-8/CXCR1 axis has also been reported to regulate cancer stem cell motility and invasion." (PMID 28860143, 2018). "CXCR1 mRNA was present in normal tissues but at a lower level than in cancer tissues." (PMID 26087179, 2015). "Besides, CXCR1/2 agonists are the primary mediators of cancer-promoted NETosis." (PMID 35585567, 2022). "Thus, neutralizing antibodies to CXCL8 or antagonists towards CXCR1/2 to disrupt CXCL8–CXCR1/2 interaction may improve the efficacy of current cancer treatment." (PMID 36612163, 2022). "Moreover, depletion of secreted IL-8 by neutralizing antibody also reduced the resistance to GEM suggesting cancer cells may enhance GEM resistance via an autocrine IL-8/CXCR1/2 loop." (PMID 27531902, 2016).
cancer (continued). "Results of the clinical study using a reparixin-paclitaxel combination in HER-2 negative breast cancer may highlight the potential for the use of CXCR1/2 small molecule antagonists as a viable strategy for the treatment of cancer, most likely in combination with established chemotherapies." (PMID 24276377, 2013). "In addition to the lack of a homologous genetic model, efforts to determine the function of CXCL8 in cancer progression are complicated by redundancy of the chemokines that share CXCR1 and CXCR2, and by the expression of cytokines other than CXCL8 in response to an upstream stimulus." (PMID 24224100, 2013). "Second, secreted CXCL1/IL8 binds to C-X-C motif chemokine receptor 1/2 (CXCR1/2), activating the AKT-BCL-2 pathway to enhance cancer cell survival and suppress NK cell function by downregulating NKG2D, TRAIL, and IFN-γ expression." (PMID 42185071, 2026). "Interleukin-8 (IL-8), overexpressed in multiple cancer types, recruits neutrophils to the TME through CXCR1 and CXCR2, influencing TAN formation." (PMID 40160822, 2025). "CXCR1 and CXCR2 are expressed in various cell types including immune cells, fibroblasts, endothelial cells, osteoclasts, and cancer cells." (PMID 39766038, 2024). "Several approaches have been developed to target NETosis in preclinical cancer models such as removal of NETs using DNase I, inhibition of the enzyme peptidylarginase deiminase 4 (PAD4) through GSK484, or blockade of the CXCR1/2 axis with reparixin." (PMID 39700646, 2024). "IL-8 binds to CXCR1 and CXCR2 receptors—expressed by immune and endothelial cells, and by most cancer cell types—activating different downstream signaling pathways, including PI3K/AKT, MAPK, and PKC." (PMID 39143551, 2024). "IL-8, acting through C-X-C chemokine receptor type 1 (CXCR1) and type 2 (CXCR2), modulates multiple signalling pathways, enhancing the angiogenesis, proliferation, and migration of cancer cells." (PMID 39199570, 2024). "IL-8 is a chemokine of the CXCL family that binds to two G-protein coupled receptors, CXCR1 and CXCR2, expressed on myeloid cells, endothelium, and cancer cells." (PMID 39639338, 2024). "In the context of cancer aggressiveness, ELR+CXCL chemokines (CXCL1, 2, 3, 5, 6, 7, 8) and their receptors CXCR1/2 play a pivotal role." (PMID 38397987, 2024). "Apart from helping to maintain homeostasis and physiological communication, both CXCR1 and CXCR2 have been shown to be aberrantly expressed or activated in various cancer types, including PCa." (PMID 39766038, 2024). "Inflammatory CAF-derived factors promote cancer cell migration by stimulating the chemokines CCR2, CCR5, and CXCR1/2 expressed by cancer cells and Ras-activating receptors." (PMID 37978384, 2023). "The chemokine CXCL8 (also known as interleukin-8, abbreviated IL-8) and its G-protein-coupled receptors CXCR1 and CXCR2 are crucial elements in this process, and also the development of many cancers." (PMID 37433790, 2023). "Some previous studies have reported that mast cells express different chemokine receptors, such as CCR2, CCR5, CXCR1, or CXCR4, in different cancers (19-, 21)." (PMID 37042867, 2023). "We have demonstrated a significant correlation between CXCR2 expression and cancer cell MMP9 in ESCC tissues (p = 0.010) through IHC, and the expression ratio of CXCR2 to CXCR1 was the highest in TE-10 among the three ESCC cell lines on Western blot." (PMID 37296952, 2023). "From our literature review, lung cancer appears to be the only cancer with the investigation of miRNA and CXCL6 regarding CXCR1 and CSCs." (PMID 36831112, 2023). "Therefore, it may be that CXCR-2 is more involved than CXCR1 in cancer suppression." (PMID 35804329, 2022). "In this section, we briefly report an overview of investigational drugs targeting IL-8 and its receptors CXCR1/CXCR2, and discuss their therapeutic potential in the field of cancer resistance." (PMID 36591453, 2022).